PPARA (peroxisome proliferator activated receptor alpha)
Diseases named in the same sentence as PPARA in open-access papers (continued):
Sharing a sentence is not in itself a finding about the gene and the disease.
Obesity (continued). "In addition, the activation of AHR/CD36 pathway promotes hepatic steatosis in mice, while inhibiting the activity of AHR and altering the expression levels of CYP1B1, PPARα, and SCD-1 that attenuate the diet-induced obesity and hepatic steatosis in mice." (PMID 34722615, 2021). "Peroxisome proliferator-activated receptor α (PPARα) regulates lipid metabolism, but its role in circadian-related obesity is not clear." (PMID 33052228, 2020). "To date, the effect of a PPARa/γ dual agonist, such as tesaglitazar, on macrophage populations in adipose tissue during obesity and dysmetabolism has not been reported." (PMID 31903139, 2020). "For this, we used High Fat Diet (HFD) feeding as a model of obesity in C57BL/6 J male Wild-Type mice (WT), in whole-body Pparα- deficient mice (Pparα−/−) and in mice lacking Pparα only in hepatocytes (Pparαhep−/−)." (PMID 32300166, 2020). "Then, we questioned whether hepatocyte and wholebody deletion of Pparα (Pparα−/− and Pparαhep−/− mice) induces overlapping responses in HFD-induced obesity." (PMID 32300166, 2020). "In animal models, capsaicin has also been shown to suppress ghrelin release, increase adiponectin mRNA expression in the adipose tissue and PPARα/PGC-1α mRNA in the liver, enhance AMPK and regulate gluconeogenesis and glycogen synthesis genes, thus reducing obesity-induced insulin resistance." (PMID 32962190, 2020). "In our previous study, DBZ inhibited HFD-induced obesity in mice by selectively activating PPARγ to a significant level and PPARα to a moderate level, but it did not activate PPARβ/δ." (PMID 31336903, 2019). "Indeed, PG extract increased thermogenic gene expression (such as SIRT1, PPARα, UCP1, PGC1α), thereby inducing the browning of white adipose tissue, resulting in an anti-obesity effect." (PMID 31615016, 2019). "Additionally, lipolysis related Aspg, and fatty acid oxidation-related PPARA and PTEN canonical pathways were elevated in BAT more than VAT of HFD fed mice indicating BAT to have a higher ability to “burn the FAT” in obesity." (PMID 29507687, 2018). "Importantly, Tfe3 KO mice showed down‐regulation of genes involved in thermogenesis, including Ucp1 and Ucp3, and oxidative genes such as Pparα in the BAT, which account, at least partially, for their reduced energy expenditure and diet‐induced obesity." (PMID 28283651, 2017). "In this study, cinnamon polyphenol increased PPARα and IRS expression in the liver; this may have potential insulin sensitizing effect and may increase IR in a rat obesity model." (PMID 28396714, 2017). "In particular, this study demonstrates that OLE exerts beneficial effects against obesity by overexpressing sirtuin 1 (SIRT-1), peroxisome proliferator-activated receptor alpha (PPARα), and peroxisome proliferator-activated receptor gamma (PPARγ), coactivator 1 alpha (Pgc-1α)." (PMID 27303302, 2016). "The PPARA/RXR and FXR and PXR/RXR activation pathways were also identified in BPS-treated preadipocytes and they have all been shown to modulate adipogenesis, lipid metabolism or obesity." (PMID 27685785, 2016). "Fenofibrates, a class of PPARα agonists, were also shown to improve hepatic steatosis in a mouse model of hereditary fatty liver in absence of obesity or diabetes and in OLETF rats, which spontaneously develop NAFLD." (PMID 23024649, 2012). "Although DEHP limited weight gain in WT mice PPARα-humanized mice were not protected against diet-induced obesity, demonstrating that this beneficial effect is limited to mPPARα activation." (PMID 20123618, 2010). "The regulatory effect of fenofibrate on obesity is not mediated through leptin since PPARα-knockout mice that become obese with age are not hyperphagic." (PMID 20871824, 2010). "PPARα may also stimulate TAG turnover by regulating transcription of acyltransferases (e.g., diacylglycerol acyltransferase) and lipases (e.g., adipose tissue TAG lipase (ATGL)) in the heart in obesity/T2D." (PMID 40663803, 2025).
Obesity (continued). "Importantly, these exosomes demonstrate a regulatory role in NRs such as PPARα, PPARγ, PPARδ, RORα, ERα, and ERβ, across a range of chronic diseases, including AIDS, atherosclerosis, cancer, CRS, diabetes, NASH, neurological diseases and obesity." (PMID 39327610, 2024). "Additionally, compound 1 (procyanidin B2) activated fatty acid oxidation regulators, PPARα and CPT1A, and suppressed fatty acid synthesis by downregulating fatty acid synthase (FAS) expression, emphasizing its potential role in modulating obesity-related markers in 3T3-L1 preadipocytes." (PMID 38613069, 2024). "CGA notably inhibits the activities of FAS, HMGCR, and ACAT, and boosts the expression of PPARα in the liver, also inhibiting HMGCoA activity and enhancing CPT activity by activating AMPK, thus promoting lipid metabolism, reducing TC synthesis, and attenuating fat absorption to combat obesity." (PMID 39459158, 2024). "In this study, we hypothesised that the previously reported anti-obesity effects of CPEF in db/db mice are due to the induction of UCP1 and PPARα expression, and accordingly quantified UCP1 and PPARα expression, and protein oxidation levels in brown adipose tissue." (PMID 36835279, 2023). "However, the mechanisms of such suppression appear to differ between the 2 mouse models of genetic obesity, with hepatic FASN deficiency attenuating PPARα activity and activating AMPK in ob/ob mice but not in Mc4r-KO mice." (PMID 37681411, 2023). "Altered DNA methylation in promoters of transcription factor genes (PPARA, KLF15, NR3C1, RORA and ATF4) known to regulate FGF21 expression and its binding receptors and co-factors (FGFR1, FGFR3 and FGFRL1 and KLB) has been revealed in relation to the elevated levels of circulating FGF21 in obesity." (PMID 33670024, 2021). "In addition, the activation of PPARα by chronic fenofibrate administration increases the gene expression of PGC1α and irisin, and it yields UCP-1-positive beige cells in the sWAT of the mice with HFD-induced obesity." (PMID 34445679, 2021). "Interestingly, mice lacking only hepatocyte-PPARα developed steatosis spontaneously but without obesity in aging." (PMID 34445672, 2021). "Both PPARα and UCP2 could exhibit different expressions according to the level of obesity, and in the state of high lipid accumulation because of HFD, PPARα and UCP2 expression could have increased as an adaptive response to prevent the generation of ROS in the mitochondria." (PMID 34948353, 2021). "Moreover, PPARα activation resulted in a reversal of whitening, with the favored thermogenesis being sustained by enhanced β3-adrenergic stimulation, lipolysis, and β-oxidation in BAT of the mice with HFD-induced obesity." (PMID 34445679, 2021). "Because impaired lipid metabolism leads to obesity and related metabolic diseases, such as dyslipidemia, atherosclerosis, type 2 diabetes, and nonalcoholic fatty liver disease (NAFLD), improved PPARα activity is required to prevent or treat this group of disorders." (PMID 33916086, 2021). "Mice only lacking Pparα in hepatocytes spontaneously develop steatosis without obesity in aging." (PMID 32300166, 2020). "Our results suggest that HBO may enhance PPARα expression in skeletal muscle in a pattern similar to PPARα agonists, which is likely part of its mechanism of action in protecting against HFD induced fatty acid metabolism dysfunction and obesity." (PMID 31906305, 2020). "Also, PPARα (peroxisome proliferator-activated receptor alpha) and SREBP (sterol regulatory element-binding protein 1) mediate a major rewiring of the hepatic circadian transcription of lipid-related genes in a mouse model of diet-induced obesity." (PMID 31092281, 2019). "PPF did not alter the PPARα mRNA level, suggesting that activation of PPARα may not be necessary for the anti-obesity effects of PPF." (PMID 31514294, 2019).
Obesity (continued). "In the present study, basing on AMPKα- PPARα/SREBP-1c signal pathway, we compared hepatic lipid metabolism of lean and DIO mice with E. coli intranasal instillation, to determine whether acute infection could exacerbate lipid disturbance in obesity." (PMID 30398974, 2018). "The potentiation of β3-adrenergic stimulatory effects by the natural cardioprotective PPARα agonist OEA might also help to lower the effective dose of the β3-adrenergic agonist, reducing the unwanted cardiovascular effects of this class of anti-obesity agent." (PMID 24159189, 2014). "This study provides evidence that combining β3-adrenergic stimulation with PPARα activation can promote metabolic effects that stimulate energy expenditure, including UCP1-mediated thermogenesis, providing a potential therapeutic approach for the treatment of obesity." (PMID 24159189, 2014). "Thus, cafeic acid and oleuropein could allow adequate PPARα activation and fatty acid utilization, increasing the OHADH activity under obesity conditions, reducing triacylglycerol accumulation in cardiac muscle." (PMID 20958965, 2010). "Similarly, SREBP1, PPARα/γ, NR3H1 and LEP were identified as common regulatory factors for fatty acid metabolism, cholesterol efflux and triglyceride metabolism in zebrafish and mammalian obesity." (PMID 20961460, 2010). "The increased level of PPARα measured in the liver of KOmice could be suspect of exerting to negative effect on insulin action and obesity." (PMID 17389764, 2007). "It is also conceivable that a potential excess of fatty acyl‐CoA levels in the muscle of males/females with obesity or T2D could lead to feedback inhibition of the ACS, either directly or by regulating the activity of transcription factors, such as PPARα and –γ." (PMID 37726199, 2023). "However, it may not faithfully recapitulate obesity since monomeric CtBP2 is rather a gain-of-function state in the interaction with PPARα." (PMID 37286039, 2023). "Thus, the sustained activation of PPARα when linked to the absence of ACOX1 activity attenuates the metabolic consequences of leptin deficiency, due to the ob/ob genotype, showing less obesity with the recovery of glucose homeostasis and alleviating insulin resistance." (PMID 34445672, 2021). "Furthermore, as obesity increases the plasma free fatty acid level, PPARα may be activated LD-dependently, non-dependently, and persistently." (PMID 33466690, 2021). "Studies have shown that the peroxisome proliferator-activated receptor alpha (PPARα) -dependent activation and promotion of fatty acid utilization in the liver induces the production of 3-HB, but the relevant mechanism deeply related to obesity-T2DM is not clear yet." (PMID 32920548, 2020). "Treatment with a specific PPARα agonist, Wy 14,634, in various mouse models with metabolic deregulations such as lipoatrophic diabetes, spontaneous fatty liver in the absence of obesity or T2D, NAFLD and NASH resulted in improved dyslipidaemia, insulin resistance and hepatic steatosis." (PMID 25500563, 2014). "However, signal cross-talk between PPARα and ERs in the regulation of obesity is not clear." (PMID 20871824, 2010). "Activation of PPARα does not, however, appear to have a major role in the anti-obesity effect of CLA, because CLA reduced body fat content in PPARα knockout mice." (PMID 15642120, 2005). "The effects of CR in the AT on PPARα and PPAR-β/δ have not been shown yet, but it is known that CR and PPARγ agonists can improve the reduced mitochondrial function in the WAT due to aging and obesity." (PMID 30037087, 2018).
Obesity (continued). "It specifically inhibited the transactivation activity of PPARγ, but not that of PPARα, β/δ and LXR α,β, by repressing the adipocyte differentiation and ameliorating obesity, insulin resistance, steatosis and hyperlipidemia in diet-induced obesity mice." (PMID 27283034, 2016). "However, thecontribution of PPARα to total body weight is ambiguous,with conflicting reports of substantial age-related obesity versus no significant body weight effects in congenic 129/SvJae or C57BL/6N Ppara−/− mice." (PMID 17389768, 2007). "Although the blood glucose lowering effect of MD001 was lower than that of rosiglitazone, the MD001-mediated increase in fatty acid oxidation via PPARα activation suggests that MD001 may have favourable effects on hyperlipidaemia and obesity without inducing body weight gain, at least in part." (PMID 30733541, 2019). "Therefore, rather than, or in addition to, activation of PPARα, dietary EPA and DHA, especially in the form of krill preparations, might produce their effects on fasting triglycerides in obesity by re-equilibrating endocannabinoid levels and CB1 receptor tone." (PMID 23706001, 2013).
Hepatic steatosis (645 papers, 2007 to 2026). Steatosis is a term used to denote lipid accumulation within hepatocytes. "PPARα is a major regulator of hepatic β-oxidation and microsomal ω-oxidation, and induces a decrease in the expression of hepatic steatosis-associated substances by enhancing mitochondrial β-oxidation." (PMID 40487402, 2025). "A recent study demonstrated that the AMPK/PPARα signaling pathway was implicated in hepatic steatosis." (PMID 39619961, 2024). "Decreased FAD due to vitamin B2 deficiency induces fatty liver disease, which is associated with the inhibition of the PPARα pathway." (PMID 38668346, 2024). "Acting as a partial agonist of peroxisome proliferator-activated receptor alpha (PPARα), a ligand-activated transcription factor associated with hepatic steatosis, silibinin protects against NAFLD in mice by reducing lipid accumulation." (PMID 37731666, 2023). "To evaluate the beneficial effects of PPARα on fatty liver caused by excessive sucrose intake, we investigated the molecular mechanisms related to the development of fatty liver in PPARα-deficient mice that were fed a high-sucrose diet (Suc)." (PMID 36140300, 2022). "The decrease in these miRNAs targeting PPARα mRNA by a deficiency of IRE1α leads to exacerbated hepatic steatosis in both in vivo and in vitro diet-induced NAFLD models." (PMID 36551797, 2022). "Prenatal hyperandrogenism induces a decreased expression of Pgc1a and PPARα and overexpression of PPARy, Srebp, Chrebp, thus being more susceptible to hepatic steatosis and damage." (PMID 36296646, 2022). "It has also been demonstrated that PPARα-deficient mice have an impaired response to fasting and promote the development of fatty liver." (PMID 35628280, 2022). "In this study, SS, a natural food compound, caused PPARα-mediated autophagy, which relieved fatty acid buildup in the liver, increased β-oxidation, and alleviated hepatic steatosis through the activation of lipophagy." (PMID 36552704, 2022). "Despite the upregulation of PPARα and numerous PPARα target genes involved in fatty acid oxidation, an HF diet causes the development of fatty liver." (PMID 36140300, 2022). "Repressed PPARα-driven fatty acid oxidation caused by sustained mTORC1 activation contributes to the development of ethanol-induced hepatic steatosis and inflammation." (PMID 34267188, 2021). "The disturbance of the PPARα signaling pathway will reduce fatty acid oxidation and cause aggravated liver steatosis and inflammation." (PMID 35003311, 2021). "The hepatic steatosis Med1 KO causes PPARα-dependent steatosis, in line with the coactivator functions of the liver and PPARα." (PMID 34830341, 2021). "PPARα is a key factor for regulating fatty acid oxidation, and PPARα deficiency aggravated multiple factors-induced hepatic steatosis in the development of NAFLD through attenuating fatty acid oxidation 24-27." (PMID 34803499, 2021). "Our data support the causal role of the RAGE/PPARα pathway in hepatosteatosis and provide novel insights into aging‐induced fatty liver." (PMID 32936538, 2020). "We have previously shown that mice with a hepatocyte-specific deletion of PPARα (PparaHepKO) had worsened hepatic steatosis on a HFD that also caused significantly higher plasma triglycerides and ApoB100 levels." (PMID 33390979, 2020). "Hepatic PPARα and circulating ketone bodies, indicators of FA utilization, were significantly low in hepatic steatosis/steatohepatitis in patients with citrin deficiency, a relatively common urea cycle disorder in the Asian population." (PMID 32192216, 2020). "Loss of PPARα repression in LKO mice improved liver steatosis upon HFD feeding and improved fibrosis upon feeding a methionine-choline-deficient diet (MCD), due to increased lipid burning as detected by elevated ketone body levels." (PMID 31293521, 2019). "PPARα serves as a crucial regulator of lipid metabolism in liver, while its deficiency can induce liver steatosis." (PMID 30079055, 2018).